FOXA2 (forkhead box A2)
Diseases named in the same sentence as FOXA2 in open-access papers (continued):
Sharing a sentence is not in itself a finding about the gene and the disease.
diabetes (30 papers, 2012 to 2025). "A previous report has indicated that a heterozygous missense variant in FOXA2 can cause monogenic diabetes." (PMID 37670346, 2023). "A recent study reported that heterozygous missense variants in FOXA2 can lead to monogenic diabetes." (PMID 36749553, 2023). "Another recent study reported a patient with diabetes due to a heterozygous missense variant in FOXA2, indicating that FOXA2 defect can lead to MD18." (PMID 33473118, 2021). "FOXA2 has been identified as an essential factor for pancreas development and emerging evidence supports an association between FOXA2 and diabetes." (PMID 33473118, 2021). "Furthermore, we discuss the consequences of FOXA2 dysregulation, including impaired α- and β-cell maturation, loss of functional identity, and contributions to the pathogenesis of diabetes." (PMID 41959739, 2025). "Moreover, our findings demonstrated that several lncRNAs, downregulated upon FOXA2 deletion are known to be linked to diabetes." (PMID 37670346, 2023). "Additionally, a recent study reported a patient with diabetes caused by a heterozygous missense variant in FOXA2." (PMID 37670346, 2023). "Finally, Foxa2 has also been implicated in the regulation of Hnf4a and Hnf1a, involved in HI and monogenic diabetes." (PMID 35422763, 2022). "STZ treatment also suppressed expression of a wide range of genes linked with key β-cell functions or diabetes development, such as G6pc2, Slc2a2 (Glut2), Slc30a8, Neurod1, Ucn3, Gad1, Isl1, Foxa2, Vdr, Pdx1, Fkbp1b and Abcc8, suggesting global β-cell defects in STZ-treated islets." (PMID 23828045, 2013). "Foxa2 is an insulin-regulated liver transcription factor whose activation leads to oxidation of fatty acids and secretion of triacyglycerols, and whose impairment has been implicated in diabetes." (PMID 24266983, 2013). "In summary, the transcriptional regulators Foxa1 and Foxa2 share a significant fraction of cis-regulatory elements that contain a high-affinity forkhead binding site and regulate genes essential in development and those implicated in etiology of diabetes." (PMID 22737085, 2012). "FOXA2 plays a central role in the differentiation and functioning of pancreatic α and β cells, hepatocytes, and dopaminergic neurons, whose dysfunction causes diseases such as, diabetes and Parkinson's disease." (PMID 23118920, 2012). "When take in conjunction with our recent findings demonstrating that deficiency of FOXA2 impairs pancreatic islet development and may lead to diabetes, these observations suggest the involvement of the alterations in lncRNA expression reported in this study may play a role in this effect." (PMID 37670346, 2023). "However, a more recent study identified a patient with diabetes due to another FOXA2 mutation." (PMID 33473118, 2021). "Insights from mouse models, human stem cell-derived islets, and patient genetics underscore the clinical relevance of FOXA2 in monogenic and complex forms of diabetes." (PMID 41959739, 2025). "On the top list of enriched biological pathways affected by the downregulated DEGs in FOXA2–/– islets, pancreatic islet development, glucose hemostasis, and diabetes were significantly enriched." (PMID 38916841, 2024). "Novel VaD loci were associated with hypertension, diabetes, and neuron maintenance (SPRY2, FOXA2, AJAP1, and PSMA3)." (PMID 39046104, 2024). "Transient HI followed by impaired glucose tolerance and diabetes was also described in FOXA2-related CHI." (PMID 37065762, 2023). "For genes variable in liver, we found enrichment for TFs involved in diseases such as cancer (e.g. Evi1, Z-score = 9.9) and diabetes (e.g. Foxa2, Z-score = 8.5)." (PMID 35485945, 2022). "The rs11257655 risk allele shows allele-specific binding to FOXA1/FOXA2, thereby upregulating the transcription of CAMK1D, which increases gluconeogenesis and, therefore, the risk of diabetes." (PMID 33919522, 2021).
diabetes (continued). "The risk haplotype preferentially binds FOXA2, increases H3K27Ac histone marks, upregulates GCKR expression, enhances glucose metabolism, and, therefore, is associated with the risk of diabetes." (PMID 33919522, 2021). "FOXA2 is involved in diabetes and response to hyperglycemia by regulating alpha‐cell differentiation and glucagon secretion." (PMID 30338211, 2018). "Metabolic processes controlled by Foxa2, such as glucose and lipid homeostasis, are often deregulated in metabolic syndromes such as diabetes and obesity." (PMID 24875183, 2014). "Understanding FOXA2's regulatory networks may open new avenues for therapeutic strategies aimed at restoring or preserving β-cell function in diabetes." (PMID 41959739, 2025). "In summary, FOXA1 and FOXA2 control glucose metabolism by regulating multiple target genes in the pancreas, liver, and adipose tissue and are potential therapeutic targets for patients with diabetes." (PMID 38605023, 2024). "FOXA1 and FOXA2 not only play a key role in organ development but also participate in the reprogramming of glucose and lipid metabolism, and they are targets for preventing and treating diabetes, fatty liver, obesity, cholestasis, and cancer." (PMID 38605023, 2024). "Taken together with other recent reports, our findings suggest that FOXA2 defects may lead to monogenic diabetes based on the gene dosage." (PMID 33473118, 2021). "We hypothesized that fetal diabetes exposure will promote the phosphorylation of FOXA2, leading to decreased FOXA2 transcription activity in AECII and fetal lung development disorders." (PMID 30338211, 2018). "It is important to note here that the rat diabetes model used in this study induced diabetes early in the pregnancy, and FOXA2 is expressed in AECII late in gestation so there may be some differences between this model and actual gestational diabetes mellitus." (PMID 30338211, 2018). "This suggests that the absence of FOXA2 leads to an increase in the expression of diabetes-associated miRNAs, which could serve as biomarkers for predicting and diagnosing diabetes." (PMID 38916841, 2024). "Together with previous published work, our data provides better understanding of the molecular control of metabolism by SIRT1 and FOXA2, and therefore may contribute to the development of intervention strategies for metabolic derangements like diabetes or obesity." (PMID 24875183, 2014). "Interestingly, Foxa1 and Foxa2 also occupy cis-regulatory elements of many diabetes susceptibility genes, both those mutated in MODY (mature onset diabetes of the young) and those with alleles associated with diabetes risk identified by genome-wide association studies (GWAS)." (PMID 22737085, 2012). "Another lncRNA that showed a strong correlation with FOXA2 and was downregulated in our study is SLC25A3, which its suppression has been reported to contribute to diabetes development by reducing ATP levels." (PMID 37670346, 2023). "These open chromatin regions were significantly enriched in binding sites of CUX2 and HNF6 as well as several other TFs with previously established functions in pancreatic development and links to monogenic diabetes, including HNF1B, FOXA2, and PDX1." (PMID 31883919, 2020). "It should further be noticed that genes of importance for islet function and diabetes such as PDX1, TCF7L2, FOXA2, FOXO1, NEUROD1 and BACH2 have C1, C3 or both these sites at their ATAC-seq open chromatin regions." (PMID 31123324, 2019). "Therefore, the aim of the present study was to explore the impact of diabetes exposure on lung development and the events affecting the function of FOXA2 in the lung of rats from mothers with diabetes and to analyze whether the related regulation is mediated by the Akt signaling pathway." (PMID 30338211, 2018).
diabetes (continued). "Because of the importance of pancreatic β-cells in diabetes, further understanding of the molecular regulatory pathways of FOXA1 and FOXA2 in pancreatic β-cell development and insulin secretion might provide therapeutic prospects." (PMID 38605023, 2024). "Even though there was no change in total FOXA2 expression in fetal lungs, our results suggest that diabetes exposure reduces the activated nuclear FOXA2 through Akt phosphorylation." (PMID 30338211, 2018).
prostate carcinoma (30 papers, 2007 to 2025). A carcinoma that arises from epithelial cells of the prostate gland. "We also identified groups that contained validated prostate cancer oncogenes with novel associations, such as SOX4, a prostate cancer transforming oncogene, and FOXA2 and GATA4, known pioneer factors (oTFCG13)." (PMID 30314329, 2018). "The mutual exclusivity of FOXA1 and FOXA2 mutations in prostate cancer and EC might seem counterintuitive given that they share diverse embryonic functions and broad expression across the endoderm and its derivatives." (PMID 35703180, 2022). "Based on its role in prostate cancer, FoxA2 may be associated with the invasive property of neonatal stem cells." (PMID 27081082, 2016). "FOXA1 and FOXA2, members of this family, are known to interact with AR to regulate transcriptional programs in prostate cancer." (PMID 40898340, 2025). "ASCL1 mediate terminal neuroendocrine differentiation of prostate cancer by regulating lineage-determinant transcription factor FOXA2." (PMID 39470735, 2024). "FOXA1 has similar expression in all Gleason grades of prostate carcinomas while FOXA2 has been found in some prostate cancer with high Gleason scores and in neuroendocrine small cell carcinomas." (PMID 39470735, 2024). "This rule is no longer invariable, as important exceptions have been described, such as the forkhead box A2 gene (FOXA2), which plays a role in prostate cancer and whose promoter methylation leads to activation of the FOXA2 gene expression." (PMID 37626776, 2023). "In other words, FOXA1 is an oncogene in prostate cancer, whereas in EC, the evidence has suggested that FOXA2 is a tumor suppressor." (PMID 35703180, 2022). "We then compared the levels of PHF8 and FOXA2 in seven paired‐prostate cancer specimens collected before and after treatments with abiraterone, enzalutamide or docetaxel." (PMID 33009820, 2021). "FOXA2 is a pioneer and endodermal transcription factor expressed in several tumour types including genitourinary cancers, such as bladder carcinomas and prostate cancer and playing a crucial role in cellular differentiation." (PMID 33448076, 2021). "For example, in prostate cancer, cancer-specific EP interactions involve enhancers that are enriched for and are activated by oncogenic TFs such as FOXA2." (PMID 34298745, 2021). "As controls, 2102EP EC cells and PC3 prostate cancer cells (positive control for FOXA2) were included." (PMID 31130628, 2019). "For CpGs with lower methylation in the prostate cancer tissues in comparison with the adjacent-unaffected tissue, there were two TFs with significant overlap that were bound in these regions: FOXA2 and SETDB1." (PMID 28412973, 2017). "K6R mutation also downregulated FOXA2 protein levels in HepG2 hepatocellular carcinoma cells, HCT116 colon cancer cells and LNCaP and DU145 prostate cancer cells." (PMID 23118920, 2012). "Similarly, in prostate cancer, the inhibition of the AR pathway activates changes in the FOXA2-dependent transcriptional pattern, driving the adeno-to-neuroendocrine transition, thereby causing castration resistance." (PMID 40032852, 2025). "In addition, FOXA2 participates in manipulating various cancers, including endometrial cancer, gastric cancer, and prostate cancer." (PMID 39129202, 2024). "Our current research identified a previously unknown PHF8/FOXA2 axis in prostate cancer as well as its role in NEPC development." (PMID 33009820, 2021). "Therefore, targeting the Siah/HIF/FoxA2 axis should inhibit the NE phenotype, sensitizing tumors to traditional prostate cancer therapy." (PMID 21037926, 2010). "Furthermore, defining the regulatory axis consisting of Siah2 and HIF-1α/FoxA2 cooperation suggests novel therapeutic modalities to treat these most aggressive forms of prostate cancer." (PMID 21037926, 2010).
prostate carcinoma (continued). "The findings that Siah controls levels and activity of HIF-1α, which cooperates transcriptionally with FoxA2 to promote NE tumor development or formation of NED of human prostate cancers, provide a rationale for targeting the Siah/HIF/FoxA2 axis as a new therapeutic modality." (PMID 21037926, 2010). "FoxA1 and FoxA2 are important regulators of epithelial proliferation and differentiation during prostate development that exhibit altered patterns of expression in human prostate cancer." (PMID 17343742, 2007). "For instance, FOXA2, by interacting with JUN, activates lineage plasticity enhancers, driving prostate cancer cells to transition from AR-dependence to a multilineage state." (PMID 40032852, 2025). "ASCL1 and ASCL2 are mutually exclusive during NEtD in prostate cancer, similar with the relationship between MYCL and MYC in SCLC and FOXA2 and FOXA1 in NEPC." (PMID 39372390, 2024). "In human prostate cancer cells, this metal complex disrupted the LSD1-H3K4me2 interaction and enhanced the amplification of p21, FOXA2, and BMP2 gene promoters." (PMID 31801559, 2019). "Forkhead box (FOX) transcription factor family members FOXA2 and FOXP1 were also among the proteins with binding sites most strongly associated with negative TMRs and have both previously been implicated in prostate cancer." (PMID 41036619, 2025). "Conversely, in prostate cancer, FOXA2 mutations are rare/absent, whereas FOXA1 mutations are common, with diverse experimental evidence that different classes of FOXA1 mutations in prostate cancer are dominant and gain of function." (PMID 35703180, 2022). "These FOXA2-dependent enhancers engage in EP interactions that are specific to tumour cells and influence the expression of key oncogenes, such as the Androgen Receptor (AR) and DLX1 in prostate cancer." (PMID 34298745, 2021). "The importance of Siah/HIF/FoxA2 axis in the formation of TRAMP NE tumor and NED of human prostate cancers suggests this signaling pathway may play a key role in the prostate stem cell function." (PMID 21037926, 2010). "Although FoxA2 may play a role in prostate cancer progression to androgen independence, it is not expressed in C4-2B cells (data not shown)." (PMID 18997859, 2008).
hepatocellular carcinoma (26 papers, 2010 to 2024). A malignant tumor that arises from hepatocytes. "In hepatocellular carcinoma, FOXA2 suppresses metastasis partially through matrix metalloproteinase-9 inhibition." (PMID 36289750, 2022). "To validate the role of FOXA1/2 in Rbfox2 regulation, we knocked down Foxa1 and Foxa2 in mouse hepatoma Hepa1-6 cells, which led to a significant decrease in Rbfox2 expression." (PMID 36536133, 2022). "For example, FoxA2 increases fatty acid oxidation, decreases obesity, regulates Cyp2b9, and represses hepatocellular carcinoma only in female mice." (PMID 32155178, 2020). "MiR-29 expression in human hepatoma cells is controlled by forkhead box A2 (FOXA2), a key gene in hepatic energy homeostasis." (PMID 33195407, 2020). "A PLA assay performed on the human hepatocellular carcinoma cell line HepG2, which endogenously expresses FOXA2 and SIRT1, showed interaction of these proteins." (PMID 24875183, 2014). "Moreover, a link of IKKα-mediated FOXA2 phosphorylation to hepatocellular carcinoma tumorigenesis was supported by higher levels of IKKα, phosphorylated FOXA2, and activated Notch1 in hepatocellular carcinoma specimens respect to normal liver tissues." (PMID 30154786, 2018). "More importantly, FOXA1 and FOXA2 have been found to be essential for sexual dimorphic hepatocellular carcinoma (HCC) in mice." (PMID 29138513, 2017). "Further supporting this work, a subset of SNPs occurring in hepatocellular carcinoma (HCC) can alter the binding of FOXA2, another forkhead protein, resulting in altered expression, a finding that was confirmed in patient samples on several target genes." (PMID 23420418, 2013). "Interaction of FOXA2 with many of the YST‐related genes and signalling pathways has been shown in various settings including liver development and hepatocellular carcinomas." (PMID 33448076, 2021). "Similarly, lncRNA NEF acts as an activator of its neighbor gene, FOXA2, which forms a positive-feedback loop in hepatocellular carcinoma (HCC)." (PMID 31575017, 2019). "Our findings with the human colon cancer cell line Caco-2 agreed well with previous studies on the human hepatoma HepG2 cell line co-transfected with HNF6 or its deletion mutants as well as FOXA1, FOXA2, or FOXA3 TATA-luciferase reporter constructs." (PMID 20967225, 2010). "Besides, lncRNA NEF inhibits hepatocellular carcinoma growth, metastasis, and epithelial-to-mesenchymal transition (EMT) through cis-activating FOXA2 and inactivating the Wnt/β-catenin signaling pathway." (PMID 39539669, 2024). "Thus, we screened ChiP‐seq data extracted from the ENCODE project of various activating or repressing histone marks throughout the FOXA2 genomic locus in NT2/D1 EC and HepG2 hepatocellular carcinoma cells." (PMID 33448076, 2021). "As a tumour suppressor, FOXA2 could be responsible for SLC25A13 high expression levels in liver and its downregulation in hepatocellular carcinoma (HCC)." (PMID 30995827, 2019). "Interestingly, HNF4G implies a negative regulation by interacting with FOXA1, RXRA, and HNF4A in the human hepatoma cell line and some studies have showed that interrelationships among FOXA1, FOXA2, HNF4A, and HNF4G affect transcriptional regulation." (PMID 29033978, 2017). "To this end, we measured expression levels of both FOXA2 and AGC2 in normal and hepatocellular carcinoma (HCC) cells." (PMID 30995827, 2019).
liver cancer (16 papers, 2012 to 2025). An epithelial or non-epithelial malignant neoplasm that arises from the liver. "Loss of Foxa1 and Foxa2 expression in female liver affects ERα binding to its targeted genes and thus increases DEN-induced liver cancer in female mice." (PMID 40568073, 2025). "This difference is mainly because of the difference in sex hormones between men and women, and FOXA1 and FOXA2 are also essential for sexual dimorphism in liver cancer." (PMID 38605023, 2024). "In contrast, PRAME negatively correlated with FOXA2 and AR expression in human liver cancer cell lines." (PMID 37173882, 2023). "Further studies have found that Foxa1 and Foxa2 can mediate and enhance the regulation of ERα or androgen receptor (AR) on target genes during the formation of liver cancer, thereby inhibiting (ERα) or promoting (AR) the development of liver cancer." (PMID 35096574, 2021). "There are obvious gender differences in HCC mice induced by DEN, and the defects of Foxa1 and Foxa2 can reverse this gender difference relative to the incidence of liver cancer." (PMID 35096574, 2021). "Serine107/111 phosphorylation inhibited FOXA2 transcriptional activity, derepressed FOXA2 target genes and promoted liver cancer growth." (PMID 23118920, 2012). "Seven TFs (FOXA1, FOXA2, RARG, STAT4, MEF2C, SOX18, and GXS2) have been identified to be likely to affect the metabolism, development, differentiation and proliferation of liver cancer in previous studies." (PMID 29033978, 2017). "Notably, shRNA-mediated knockdown of FOXA1 and FOXA2, along with sustained ETS1 expression, completely shifted HCC to intrahepatic cholangiocarcinoma development in primary liver cancer mouse models." (PMID 40149719, 2025).